SDC1 (syndecan 1)
Diseases named in the same sentence as SDC1 in open-access papers (continued):
Sharing a sentence is not in itself a finding about the gene and the disease.
breast carcinoma (continued). "In breast cancer, enhanced activation of integrins caused by Sdc-1 downregulation results in increased FAK activation." (PMID 32477959, 2020). "As high MD has been linked to increased breast cancer incidence, this suggests that stromal Sdc-1 expression is important for breast cancer development." (PMID 33330449, 2020). "Among PGs, syndecan-1 and -4 are associated with breast cancer and cell adhesion and mobility and were, therefore, selected as candidates for the activities of LL-37." (PMID 31547381, 2019). "In breast cancer, increased cell-membrane syndecan-1 levels are found and it is associated with high-grade tumors." (PMID 29796177, 2018). "To determine the role of host Sdc1 in metastasis, we inoculated highly metastatic 4T1 mouse mammary carcinoma cells into the mammary fat pads of syngeneic BALB/cJ wild-type or genetically Sdc1-deficient mice." (PMID 29976229, 2018). "Both carcinoma-cell-associated and stromal Sdc1 can promote breast carcinoma growth but the importance of this proteoglycan in breast carcinoma progression and metastatic spread is less clear." (PMID 29976229, 2018). "Syndecan-1 is the heparan sulfate proteoglycan associated with malignancy of various cancers, including breast cancer." (PMID 29963269, 2018). "Higher SDC1 expression was associated with higher histologic grade and inversely related to hormonal receptor status of breast cancer cells." (PMID 29963269, 2018). "Increased levels of SDC1 are associated with the malignancy of various cancers, including breast cancer." (PMID 29963269, 2018). "On one hand, as a receptor for collagen, syndecan-1 can be regulated by tumor-associated collagen signature-3, which leads to decreased collagen alignment and increased death in breast cancer patients." (PMID 30135409, 2018). "The metastatic potential of the aggressive mouse mammary carcinoma cell lines, 4T1 and E0776, was tested in wild-type and genetically Sdc1-deficient host animals." (PMID 29976229, 2018). "We showed in two mouse strains that the ability of highly aggressive mouse mammary tumor cells to metastasize to the lungs is diminished in mice genetically deficient in Sdc1." (PMID 29976229, 2018). "Our findings suggest that overexpressed SDC1 was identified in breast cancer than in matched normal tissues and is associated with methylation status of SDC1 promoter." (PMID 29340066, 2017). "Meanwhile, pooled data suggested that SDC1 mRNA expression is associated worse prognosis of breast cancer." (PMID 29340066, 2017). "In summary, overexpressed SDC1 was identified in breast cancer than in matched normal tissues and is associated with methylation status of SDC1 promoter." (PMID 29340066, 2017). "The loss or overexpression of syndecan-1 correlates with poor prognosis and aggressive phenotype in various cancers, such as breast carcinomas, colorectal cancer, prostate cancer, and HCC." (PMID 27556509, 2016). "In contrast, studies have reported that high expression levels of syndecan-1 in breast carcinoma are associated with high histological grade, high mitotic count, large tumor size, c-erbB-2 over-expression, and estrogen receptor-negative status." (PMID 26869927, 2016). "SDC1 has been shown to be expressed at high levels in breast cancer specimens and was associated with high histologic grade, large tumor size, high mitotic count, and poor prognosis." (PMID 26293675, 2015). "Previous work has shown that syndecan-1 upregulation in breast carcinoma is associated with poor prognosis, particularly when present in the stroma." (PMID 25623282, 2015). "The distribution of SDC1 to cell membrane has predominantly been described in breast cancer; however, shed SDC1 in other tumor types has been directly associated with increased invasion and cancer progression." (PMID 25140302, 2014). "The data on SDC1' roles seem to be more uniform as high expression of SDC1 has been linked with increased tumor aggressiveness and poorer prognosis in breast carcinomas." (PMID 25140302, 2014).
breast carcinoma (continued). "Loss of epithelial SDC1 was associated with a more favorable prognosis in breast cancer and SDC1 overexpression was associated with poor overall survival in estrogen receptor-negative patients." (PMID 24373193, 2013). "DHA-induced apoptosis of breast cancer cells was also associated with up-regulation of the transmembrane heparan sulfate proteoglycan syndecan-1." (PMID 22811918, 2012). "We concluded that the loss of syndecan-1 epithelial expression was of strong prognostic value in breast carcinomas." (PMID 18542065, 2008). "In accordance with its role as a signalling coreceptor, a recent study conducted in 207 breast cancer patients demonstrated a significant association of Sdc1 overexpression with the Ki67 proliferation index." (PMID 17244359, 2007). "In terms of stage analysis, SDC1 expression in tumor cells was associated with OS in patients with T1-2 and N0-1 stages, but not in those with advanced breast cancer, suggesting that SDC1 plays a crucial role in the early progression of breast cancer." (PMID 41364407, 2025). "Specifically, cytoplasmic SDC1 expression in breast cancer was associated with more aggressive behavior, while stromal SDC1 expression correlated with a better prognosis according to Kaplan–Meier survival analysis, although this was not supported by multivariate analyses." (PMID 41364407, 2025). "Meanwhile, syndecan-1 expression has been correlated with a lipogenic phenotype in advanced prostate cancer and has been linked to αvβ3 integrin activation in breast cancer." (PMID 41303628, 2025). "Furthermore, genetic alterations in pathways such as syndecan-1-mediated signaling, hepatocyte growth factor receptor signaling, and growth hormone signaling contribute to the predisposition to breast cancer." (PMID 38791246, 2024). "Similarly, syndecan-1 overexpression associated with stem cell markers phenotype has been documented in breast cancer leptomeningeal metastasis." (PMID 36088392, 2023). "Interestingly, a previous study found that SDC1+ cell lines were susceptible to indatuximab ravtansine in breast cancer." (PMID 38048216, 2023). "The present study highlights an important impact of Sdc-1 depletion on several protumorigenic breast cancer cell properties, including the CSC phenotype (associated with therapeutic resistance), cell cycle progression, apoptotic resistance, and expression of proangiogenic factors." (PMID 34070901, 2021). "The HSPGs GPC1 and SDC1, overexpressed in a high percentage of breast cancer pathologies, enhance the mitogen effects associated with heparin-binding growth factors like Basic Fibroblast Growth Factor (FGF2), HBEGF and Hepatocyte growth factor (HGF), promoting cell proliferation." (PMID 33494442, 2021). "In addition, the cleavage of syndecan-1 at a specific juxtamembrane cleavage site is implicated in the pathophysiological response in breast cancer." (PMID 34113616, 2021). "On the other hand, the observed Sdc-1 and HA-dependent changes in signaling were associated with changes in gene expression that could be linked to several phenotypes relevant to breast cancer progression." (PMID 34070901, 2021). "A non-coding region SNP in SDC4 associates with high triglyceride levels, decreased longevity, coronary artery disease and hypertension, while one SDC1 SNP in the 3′UTR was associated with an increased likelihood of breast cancer in an Australian caucasian female population." (PMID 33561383, 2021). "Syndecan-1 (SDC1) has been linked with the accelerated metastasis of breast cancer to the brain." (PMID 32873298, 2020). "Syndecan-1 is associated with breast cancer cell adhesion, migration, and resistance." (PMID 30922347, 2019). "However, the role of SDC1 in breast cancer and the underlying molecular mechanism responsible for its involvement in the generation and development of tumor are still unclear." (PMID 29340066, 2017). "Alteration frequency of SDC1 mutation in breast cancer was identified by performing cBioPortal." (PMID 29340066, 2017).
breast carcinoma (continued). "In addition, the following data mining and meta-analysis suggested that high SDC1 expression also associated with increased risk of MR and indicates significantly worse MR-free survival among patients with breast cancer." (PMID 29340066, 2017). "Breast cancer has 35.62% C > T and 20.55% G > A mutation in SDC1 coding strand." (PMID 29340066, 2017). "Recent work has shown that stromal syndecan-1 expression induces ECM alignment in breast cancer, although the underlying mechanism remains unclear." (PMID 27776346, 2016). "Syndecan-1 expression is induced in the stroma of invasive breast carcinomas in some cases, whereas other studies linked an unfavorable prognosis in breast carcinoma patients with syndecan-1 in tumor cells but a better prognosis for those lacking syndecan-1 expression within the stroma." (PMID 26420915, 2015). "Breast cancer is associated with increased cell-membrane syndecan-1." (PMID 26420915, 2015). "Importantly, SDC1 has also been linked with the promotion of proliferation of human breast cancer cells in vitro." (PMID 25140302, 2014). "Moreover, shedding and membrane-associated SDC1 play distinct roles in different stages of ERαa+ breast cancer cell progression." (PMID 25140302, 2014). "Therefore, the authors concluded that the loss of SDC1 epithelial expression was of strong prognostic value in breast carcinomas." (PMID 25140302, 2014). "Resistance of Syndecan-1-deficient mice to experimentally-induced tumorigenesis has been linked to altered Wnt-responsive precursor cell pools, suggesting a potential role of Syndecan-1 in breast cancer cell stem function." (PMID 24392029, 2013). "Of note, expression of Sdc1 is required for proper development of a β-catenin responsive mammary epithelial progenitor cell population, which appears to be the mechanistic principle underlying resistance of Sdc1-deficient mice to wnt-1 mediated breast cancer." (PMID 17244359, 2007). "However, it has shown some differences in the correlation between the Sdc1 expression and the important hormonal ER/PR status as the unavoidable prognostic/predictive factors in the routine diagnostic-therapeutic procedure of each breast carcinoma." (PMID 30151336, 2018). "Moreover, the expression of SDC1 in both epithelium and stroma may be a predictor of unfavorable prognosis in breast cancer, whereas loss of epithelial SDC1 was associated with a more favorable outcome." (PMID 25140302, 2014). "Interestingly, SDC1 expressing breast carcinomas show decreased response to chemotherapy, whereas it has also been indicated that the loss of SDC1 expression may be a potential predictive factor for response to preoperative systemic therapy." (PMID 25140302, 2014). "First, while the pan-cancer analysis of SDC1 was conducted using the TCGA dataset, functional validation through in vivo or in vitro experiments was performed only in breast cancer, leaving its precise role in other cancer types unverified." (PMID 41364407, 2025). "Silencing SDC1 in breast cancer cells inhibited their proliferation and reduced the protein levels of stem markers CD44, CD133, and SOX2." (PMID 41364407, 2025). "Immunohistochemical data from the Human Protein Atlas (HPA) revealed markedly elevated SDC1 protein expression in breast carcinoma specimens compared to normal mammary tissues." (PMID 41209699, 2025). "In vitro validation, reducing SDC1 expression inhibited cell proliferation and suppressed cancer stemness biomarker expression in breast cancer cell lines." (PMID 41364407, 2025). "Cleavage of SDC1 promotes SUMOylation of AKT highlighting a role of PI3K/AKT in SDC1‐mediated breast cancer proliferation." (PMID 40542654, 2025). "Analysis via the TISCH database indicated that SDC1 in breast cancer is primarily expressed in stromal cell and tumor cells, but not in immunity cells." (PMID 41364407, 2025).
breast carcinoma (continued). "In our research, we found that SDC1 expression in tumor cells is vital for tumor progression, particularly in Luminal, older, and early-stage breast cancer patients." (PMID 41364407, 2025). "In breast cancer, the SDC1 expressed in different partial and different subtype associated with different affection, however, the role of SDC1 in pan-cancer has been less studied." (PMID 41364407, 2025). "We then focused on breast cancer, checking SDC1 expression by immunohistochemical staining using primary breast cancer samples from Shanghai Tenth Hospital." (PMID 41364407, 2025). "In the TCGA breast cancer dataset, SDC1 expression was notably correlated with the stem cell biomarkers CD133, CD44, CD24, POU5F1, SMAD2, and NANOG at the transcriptional level." (PMID 41364407, 2025). "In breast cancer, SDC1 can act as either a favorable or unfavorable prognostic factor, depending on the hormonal status and cancer subtype." (PMID 41228316, 2025). "In the downstream analytical phase of the transcriptome data from the UALCAN platform for TCGA breast cancer revealed that the expression of SDC1 mRNA was significantly up-regulated in TNBC compared with other molecular subtypes (Luminal A/B, HER2+ sex)." (PMID 41209699, 2025). "Kaplan-Meier curves show that SDC1, NACAD, ZMAT3, CCND2, XG and SGCE are associated with prognosis in breast cancer patients." (PMID 39664194, 2024). "SDC1 participates in establishing a permissive lung microenvironment for breast cancer metastasis, while SDC4 engages with EGFR to sustain cell cycle progression in head and neck carcinoma." (PMID 38546390, 2024). "Previous studies have reported that SDC1 is a marker of epithelial–mesenchymal transition, and its overexpression can promote pancreatic and breast cancer." (PMID 37021816, 2023). "SDC1 and the AR have been identified as molecular markers with a high expression in breast cancer tissues compared to normal tissues." (PMID 36980680, 2023). "IL-6 is a known mediator of the EMT process in breast carcinomas, and it was shown that SDC1 silencing suppresses IL-6 signaling pathways, resulting in less proliferative and metastatic behavior." (PMID 36980680, 2023). "Corroborating these findings in breast cancer tissues, SDC1 and SDC4 expression levels are correlated with FGF receptor complex expression." (PMID 36980680, 2023). "Our findings also suggest that SDC1 regulates the migration of MDA-MB-231 breast cancer cells through a TGFb1-Smad and E-cadherin-dependent mechanism." (PMID 37069585, 2023). "miR-122-5p overexpression or liver-cell-derived exosomal miR-122-5p enhances the human breast cancer MCF-7 cell motility via directly targeting the SDC1 3′ UTR." (PMID 36980680, 2023). "Highly invasive human breast cancer cells MDA-MB-231 can enhance SDC1 expression in senescent fibroblasts via the paracrine action of TGF-β." (PMID 37069585, 2023). "An overexpression of miR-335-5p retards the growth, invasion, and migration of breast cancer cells via the direct targeting of SDC1." (PMID 36980680, 2023). "SDC1 is capable of modulating breast cancer stem cell phenotypes via interleukin (IL)-6/signal transducers and activators of transcription 3 (STAT3), Notch, and epidermal growth factor receptor (EGFR) signaling pathways." (PMID 36980680, 2023). "Up to this point, our data confirmed the key role of SDC1 in the EMT-related progression of breast cancer." (PMID 37056938, 2023). "This conclusion fully agrees with our observations, and a deeper understanding of the molecular mechanism of SDC1 in breast cancer should be provided in the future." (PMID 37056938, 2023). "The cleavage of SDC1 in the membrane of tumor cells is also quite important for the aggressive phenotype of breast cancer cells." (PMID 36980680, 2023). "Interference with SDC1 expression can influence multiple and interconnected signaling pathways relevant to breast cancer progression." (PMID 36980680, 2023).
breast carcinoma (continued). "Comparing infiltrating and local breast carcinomas, it was demonstrated that SDC1 is present in both the connective tissue and stroma of metastatic carcinomas, while absent in the stroma of normal tissue or local carcinomas." (PMID 36980680, 2023). "Accumulating clinical evidence has revealed that SDC1 overexpression is strongly correlated with ER and PR negativity, high-grade and large-size breast cancer tumors, and subsequent poor clinical outcomes." (PMID 36980680, 2023). "Concerning breast cancer, our previous data reported that SDC1 depletion in MDA-MB-231 cells increased cell adhesion and migration on fibronectin, but the addition of exogenous IL-6 suppressed this migratory behavior." (PMID 36980680, 2023). "Mechanistically, BPzoledronic acid exhibits an anti-breast cancer effect, namely the inhibition of cell proliferation, adhesion, migration, and invasion via the suppression of the expression of SDC1 and 2, whereas SDC4 was upregulated." (PMID 36980680, 2023). "Elevated levels of syndecan expressions in cancer can be correlated with poor outcomes, e.g., of Syndecan-1 in breast cancer and of Syndecan-2 in colorectal cancer, where it is highly associated with metastasis." (PMID 37046716, 2023). "In infiltrating human breast carcinomas, SDC1 accumulation within the tumor stroma was sought to contribute to neovascularization and stromal proliferation since HS chains usually interact with diverse heparin-binding growth factors, such as FGF-2." (PMID 36980680, 2023). "Among the immunity-related genes, SDC1 was identified as being closely related to the prognosis of breast cancer." (PMID 37069585, 2023). "Further, the broad-spectrum MMP inhibitor GM6001 curtails breast carcinoma cell growth by blocking stromal SDC1 shedding." (PMID 36980680, 2023). "In basal breast cancer, SDC1, CD4+ T cells, and DCs were negatively correlated with tumor survival; however, the associated molecular mechanism needs to be further verified." (PMID 35037689, 2022). "T47D breast carcinoma cells induce expression of SDC1 in mammary fibroblasts, whereas shedding of SDC1 HS from the fibroblast surface mediates the paracrine growth signal of breast carcinomas." (PMID 36358833, 2022). "We previously showed that in breast cancer cells, the membrane-bound and the soluble form of Sdc-1 exert different functions." (PMID 35155241, 2022). "SDC-1 is a membrane-anchored protein polysaccharide expressed on the basolateral surface of epithelial cells, which is abnormally induced in breast cancer stromal fibroblasts and plays a key role in tumor proliferation." (PMID 36277284, 2022). "Elevated expression levels of syndecan-1 have been reported in breast cancer, pancreatic cancer, and squamous cell carcinoma of the lung, whereas increased levels of syndecan-2 have been observed in melanoma and colon cancer." (PMID 35128576, 2022). "In breast cancer cells, the overexpression of WT Sdc-1 increased cell proliferation, whereas overexpression of the soluble form Sdc1 inhibits proliferation." (PMID 35155241, 2022). "Eight markers (FGF2, IL17B, IP10, MIG, MIP1d, LOX1, OPN and SDC1) found to be upregulated in primary tumours were present in higher concentration in plasma of breast cancer patients." (PMID 34997107, 2022). "SDC1 overexpression in senescent breast stromal fibroblasts induced by ionizing radiation treatment of breast cancer via an autocrine action of TGF-β reduces expression of COL1A1 and increases expression of several MMPs, i.e., MMP-1, -2, -3, and -9." (PMID 36358833, 2022). "In breast cancer, higher expression of SDC1 is correlated to worse OS and positively correlated with grade." (PMID 35037689, 2022). "Previous studies using heterologous overexpression of membrane-bound and soluble forms of murine Sdc-1 in human breast cancer cells had provided valuable insights on their differential role in invasive growth of breast cancer cells." (PMID 35155241, 2022).